SIRPA (signal regulatory protein alpha)
Diseases named in the same sentence as SIRPA in open-access papers (continued):
Sharing a sentence is not in itself a finding about the gene and the disease.
cancer (continued). "CD47, a prominent “don’t eat me” signal expressed on various cancer cells, interacts with its receptor Sirpα on macrophages to inhibit phagocytosis." (PMID 39766137, 2024). "Combined targeting of multiple immune checkpoints, particularly CD47/SIRPα and PD-1/PD-L1, has gained synergistic effects in cancer treatment." (PMID 38462636, 2024). "Coming at things from another direction, human cancer cells treated with a SIRPα blocking antibody showed cytoskeletal changes." (PMID 38362603, 2024). "In fact, several anti-SIRPA antibodies have been in development for cancer immunotherapy and tested in human clinical trials." (PMID 38920727, 2024). "In immunotherapy, blocking the CD47/SIRPα interaction can enhance the immune system’s ability to target and eliminate cancer cells." (PMID 39040441, 2024). "Inhibition of CD47 signaling has been proved to be to induce Sirpα-dependent phagocytosis, thereby enhancing the phagocytosis activity of innate cells against cancer cells and targeting the innate immune regulatory system." (PMID 38832992, 2024). "Phagocytosis of ‘self’ cells including cancer cells is generally inhibited by the macrophage checkpoint interaction between SIRPα on the macrophage and ubiquitously expressed CD47 on any target cell." (PMID 38805560, 2024). "The cancer cells were pre-treated with aPD-L1 and aCD47 antibodies for 4 hours, followed by a two-hour incubation with Dil-labeled PD-1/SIRPα NVs." (PMID 39588148, 2024). "The CD47/SIRPα pathway plays a crucial role in regulating immune responses, particularly in the context of cancer immunotherapy." (PMID 39040441, 2024). "CD47 on the cancer cell membrane and its receptor signal-regulatory protein alpha on TAMs are another pair of immune checkpoints that inhibit the activation of macrophages against cancer." (PMID 38386265, 2024). "In conclusion, our findings highlight the promising potential of PD-1/SIRPα NVs as novel therapeutic agents for cancer immunotherapy." (PMID 39588148, 2024). "By inhibiting the CD47/SIRPα interaction, the “don’t eat me” signal is turned off, allowing macrophages and other myeloid cells to recognize and phagocytose cancer cells more effectively." (PMID 39040441, 2024). "In this review, we highlight the recent progress and difficulties in CD47/SIRPα targeted drug development for cancer immunotherapy, look into future perspectives, and explore potential solutions to improve CD47/SIRPα targeted drug development." (PMID 39040441, 2024). "The protein modified in such a way gains the quality of enhanced binding of SIRPα and therefore, inhibits the cancer cell clearance performed by phagocytes." (PMID 38892394, 2024). "Blocking immune checkpoint CD47/SIRPα is a useful strategy to engineer macrophages for cancer immunotherapy." (PMID 38383737, 2024). "CD47, an immune checkpoint protein overexpressed on various cancer cells, binds to Signal Regulatory Protein alpha (SIRPα) on macrophages to deliver "don't eat me" signal that prevents phagocytosis of cancer cells." (PMID 38462636, 2024). "The CD47/SIRPα interaction between cancer cells and macrophages serves as a crucial “don’t eat me” signal, preventing cancer cells from phagocytosis by macrophages." (PMID 39588148, 2024). "CD47/SIRPα and PD-1/PD-L1 have emerged as promising targets for cancer immunotherapy, and their combined blockade has shown superior antitumor effects in preclinical studies." (PMID 38462636, 2024). "The first and very promising immune checkpoint identified on myeloid cells is the inhibitory receptor signal regulatory protein alpha (SIRPα), which interacts with integrin associated protein (IAP; CD47) on cancer cells." (PMID 39659795, 2024). "IMM0306, a fusion protein of CD20 monoclonal antibody with the CD47 binding domain of SIRPα, demonstrated excellent cancer-killing efficacy by activating both macrophages and NK cells." (PMID 39040441, 2024).
cancer (continued). "VISTA expression in THP-1 and monocyte-derived macrophages strongly downregulated expression of SIRPα, a prominent ‘don’t eat me’ signal, and augmented phagocytic activity of macrophages against cancer cells." (PMID 38553748, 2024). "Targeting CD47 on cancer cells, which binds with the SIRPα myeloid inhibitory receptor expressed on myeloid cells and makes them unresponsive against cancer cells, is a novel way of rescuing phagocytic abilities of TAMs." (PMID 38703051, 2024). "SPP1 + macrophages also showed higher expression of SIRPA expression levels compared to SPP1- macrophages across six cancer types, which was verified by subsequent mIHC assays." (PMID 39696410, 2024). "In summary, the simultaneous inhibition of CD47 and VEGF using SIRPα-VEGFR1 successfully stimulated the immune response of the host against cancer recurrence, leading to a significant extension in overall survival." (PMID 38532108, 2024). "The CD47-signal regulatory protein alpha (SIRPα) axis, discovered in the late 2000s, was the first identified checkpoint inhibiting cancer phagocytosis through innate immunity." (PMID 38971872, 2024). "Therapeutic antibodies and a SIRPα-Fc fusion decoy designed to block the interaction between CD47 and SIRPα have entered multiple clinical trials and provided anecdotal evidence for efficacy in some cancers." (PMID 38495618, 2024). "The emergence of anti-CD47 therapies aimed at impeding CD47 interaction with SIRPα to improve macrophage-mediated cancer cell clearance has attracted much attention in recent years, with monoclonal antibodies in clinical trials." (PMID 39138571, 2024). "The CD47/SIRPα signaling pathway through CD47 interacting with SIRPα on macrophages and dendritic cells, is an attractive target for cancer therapies in both solid tumors and hematological malignancies by regulating normal immune tolerance and autoimmunity." (PMID 39040441, 2024). "Therapies that block the CD47/SIRPa axis stimulate macrophage engulfment and destruction of cancer cells in preclinical models and show encouraging signs of efficacy in ongoing clinical trials for solid and hematologic malignancies." (PMID 38483480, 2024). "In conclusion, our findings highlight the promising potential of PD-1/SIRPα NVs as novel and effective ICIs for cancer immunotherapy." (PMID 39588148, 2024). "CD47 is highly expressed on many cancers, and it binds to the inhibitory receptor SIRPa that is present on macrophages and other myeloid cells." (PMID 38483480, 2024). "It should be mentioned that the prognostic significance of SIRPA expression is inconsistent across different cancer types." (PMID 38920727, 2024). "CD47 on the surface of cancer cells binds to SIRPα on macrophages to inhibit macrophage‐mediated phagocytosis." (PMID 37409429, 2023). "Several studies have demonstrated the enhanced therapeutic efficacy of dual blockade of CD47/SIRPα and PD-1/PD-L1 signaling in the treatment of different types of cancers." (PMID 36593962, 2023). "SIRPα is an inhibitory receptor that binds to CD47 on cancer cells and suppresses microglial and macrophage phagocytosis." (PMID 37483607, 2023). "CD47, a transmembrane protein expressed on the cancer cell surface, is a critical immune checkpoint via interacting with macrophage surface protein SIRPα to prevent phagocytosis." (PMID 36823443, 2023). "CD47 (cluster of differentiation 47), a glycoprotein ubiquitously expressed on the surface of various cancer cells, interacts with the SIRPα protein expressed on macrophages." (PMID 36823443, 2023). "Nowadays, SIRPα/CD47 is inhibited in combination with other checkpoint immunotherapies to treat multiple types of cancer." (PMID 36829496, 2023). "Flow cytometry analysis after incubation revealed enhanced phagocytic activity in macrophages co-cultured with MφNP-treated cancer cells compared to those cultured with SIRPα-blocked MφNPs or plain nanoparticles." (PMID 38111068, 2023).
cancer (continued). "Increasing evidence has demonstrated that blocking the CD47 interaction with SIRPα can enhance cancer cell clearance by macrophages." (PMID 38068428, 2023). "At the same time, the SIRPα knock-out alone had failed in increasing anti-cancer macrophage responses." (PMID 38017494, 2023). "The expression of CD47 on cancer cells acts as a “don’t eat me” signal to prevent cancer cells from being phagocytosed because CD47 binds signal regulatory protein α (SIRPα) on APCs, including DCs and macrophages." (PMID 37208386, 2023). "When CD47 on the cancer cell surface engages with SIRPα on MΦ, it sends a “Don’t-eat-me” signal to prevent phagocytosis of cancer cells by MΦ." (PMID 38239396, 2023). "In the TME, overexpressed CD47 on cancer cells bind to SIRPα on myeloid cells, especially macrophages, monocytes, granulocytes, and CD4+ DCs, limiting phagocytosis and intracellular degradation." (PMID 38008741, 2023). "In this study, we generated a bispecific antibody 6MW3211, which blocks both PD-1/PD-L1 and CD47/SIRPα pathways to boost both innate and adaptive immunity for cancer patients." (PMID 36593962, 2023). "Overall, our in vitro, in vivo, and patient data is consistent in that Kaiso plays a regulatory role in THBS1, CD47, and SIRPA, which are each well documented for cancer to evade immune surveillance." (PMID 37190208, 2023). "The binding of CD47 on cancer cells to signal regulatory protein-a (SIRPa) on macrophages results in the escape of cancer cells from phagocytosis." (PMID 36761751, 2023). "Previous findings based on monoclonal antibodies (mAbs) or fusion proteins that block CD47 or SIRPα have been developed in cancer research." (PMID 37456027, 2023). "CD47-SIRPα plays an important role in regulating the immune system, and CD47 can bind to the SIRPα protein on the surface of immune cells to inhibit immune cells from phagocytosing cancer cells." (PMID 37731525, 2023). "The CD47/signal regulatory protein α (SIRPα) axis, which functions as an inhibitory phagocytosis checkpoint, also serves as a key mediator in cancer immune evasion." (PMID 36787255, 2023). "Its interaction with signal-regulatory protein α (SIRPα) can help cancer cells escape phagocytosis, which is a promising anti-cancer target." (PMID 37927570, 2023). "The SIRPα/CD47 homeostatic function also occurs in the context of cancer to escape the immune system." (PMID 36829496, 2023). "The CD47/SIRPα axis is well known to mediate immune escape by promoting cancer resistance to phagocytosis." (PMID 37848444, 2023). "CD47 on cancer cells interacts with the inhibitory receptor signal regulatory protein alpha (SIRPα), which is expressed in phagocytes." (PMID 37894750, 2023). "CD47 is a surface molecule on cancer cells that functions as a “don’t eat me” signal for TAM by engaging signal-regulatory protein alpha (SIRPα), an inhibitory receptor on macrophages." (PMID 36961012, 2023). "Increasing evidence demonstrates that blocking CD47 interaction with SIRPα can enhance cancer cell clearance by macrophages." (PMID 36726125, 2023). "Multiple strategies have been devised to either block CD47 or SIRPα, and have proven effective in anti-cancer therapy." (PMID 38035101, 2023). "The intricate complex system of the differentiation 47 (CD47) and the signal-regulatory protein alpha (SIRPα) cluster is a crucial target for cancer immunotherapy." (PMID 37375166, 2023). "The interaction between CD47 and its receptor SIRPα on macrophages inhibits the phagocytosis of cancer cells." (PMID 38188674, 2023). "Therapeutic targeting the SIRPα/CD47 signaling axis is considered a promising strategy for the treatment of advanced cancers." (PMID 38164132, 2023). "The CD47/SIRPα interaction is another therapeutic target for human solid tumors: CD47 is a unique cell-surface marker expressed by human cancers; SIRPα is a protein expressed on macrophages and dendritic cells." (PMID 36827121, 2023).
cancer (continued). "When CD47 binds to SIRPα, it acts as a signaling mechanism that inhibits myeloid phagocytosis of the “self”, consequently impeding the elimination of cancer cells by phagocytes." (PMID 37894750, 2023). "RRx-001, a multi-functional drug used in clinical trials such as NCT02518958, not only can promote M1-TAM phenotype but also can be used as an inhibitor of CD47 on cancer cells and SIRPα on macrophages." (PMID 38035101, 2023). "Their simulation results showed that oxidation of CD47 reduced its binding affinity to SIRPα on innate immune cells, thereby decreasing the chance of cancer cells evading immune cells." (PMID 37759771, 2023). "It is conceivable that the fusion WT NVs platform can be extended to concurrently targeting to other checkpoints for synergetic cancer immunotherapy except PD‐1/PD‐L1 and SIRPα/CD47, such as CTLA‐4, LAG‐3, TIGIT and so on." (PMID 37974395, 2023). "Increasing studies report that targeting signal regulatory protein alpha (SIRPα)/CD47 results in therapeutic success in cancer treatment." (PMID 36829496, 2023). "The binding of CD47 and SIRPα leads to the inhibition of phagocytic activity in macrophages, which is beneficial for normal cells but also allows cancer cells to evade immune detection and elimination." (PMID 37375166, 2023). "Numerous studies have indicated that CD47 is critical for treatment, prognosis, and diagnosis of a variety of malignancies, in which the most notable function of the CD47/SIRPα axis regards cancer therapy." (PMID 36726125, 2023). "The immune immunomodulators CD276 (B7-H3) and SIRPA (SIRPα) demonstrated increased expression in the stroma of high-grade dysplasia and carcinoma regions." (PMID 36442992, 2023). "All these results confirmed that targeting the CD47/SIRPα axis can provide a new potential treatment for various cancers." (PMID 36080360, 2022). "CD47 performs a vital function in cancer therapy by binding to different SIRPα, thrombospondin 1, and integrin." (PMID 35697717, 2022). "CD47 blockades or SIRPα fusion proteins direct targeting macrophages and significantly increase both innate and adaptive immunity against many types of cancer." (PMID 36158683, 2022). "We performed a systematic review and meta-analysis of relevant databases and conference abstracts including clinical trials using CD47 and/or SIRPα inhibitors in cancer treatment." (PMID 36439116, 2022). "SIRPα expressed by TAM interacts with CD47 at the surface of cancer cells, and transmits the “don’t eat me” signal." (PMID 35163420, 2022). "CD47-SIRPα inhibition shows promise in cancer therapy; selective SIRPα blockade in combination with cytotoxic therapies in particular seem to maximize anti-tumoral benefit." (PMID 36439116, 2022). "CD47 expressed on cancer cells interacts with its ligand signal regulatory protein alpha (SIRPα) on macrophages." (PMID 36428745, 2022). "CD47/SIRPα axis is recognized as an innate immune checkpoint and emerging clinical data validate the interest of interrupting this pathway in cancer, particularly in hematological malignancies." (PMID 35538512, 2022). "Engineered SIRPα-Fc fusion is able to restore MP’s ability to phagocytize cancer cells and prime cytotoxic CD8 T cells." (PMID 35163420, 2022). "Primarily, increased cancer cell phagocytosis resulting from disruption of the CD47/SIRPα cross talk leads to enhanced presentation of antigens and CD8+ T cell proliferation in vitro." (PMID 35978372, 2022). "In the present study, our data demonstrates that CD68 and SIRPα were more highly expressed in ICC patients compared with para-cancer controls." (PMID 35317832, 2022). "While SIRPα is also expressed by certain cancer cells, it appears to inhibit their proliferation independently of its role in modulating antitumor immunity." (PMID 35229723, 2022).
cancer (continued). "Signal-regulatory protein alpha, which has recently attracted attention as a candidate target of immune checkpoint inhibitors in the field of cancer, was highly expressed on neutrophils, monocytes, and macrophages in the Burn/CLP group." (PMID 36530874, 2022). "DSP107 effectively blocked the CD47/SIRPα checkpoint and potentiated phagocytic uptake of cancer cells by macrophages and PMNs in vitro." (PMID 35287686, 2022). "Given its more restricted histological distribution, direct targeting of SIRPα is anticipated to overcome these challenges and provide an alternative strategy for cancer immunotherapy." (PMID 35256517, 2022). "CD47 was initially discovered in ovarian cancer cells but expressed in all cells and overexpressed in cancer cells as a “self-marker,” delivering an inhibitory “don’t eat me” signal by engaging in SIRPα, thereby avoiding phagocytosis by macrophages." (PMID 36497444, 2022). "Originally, the antitumor activity of CD47/SIRPα axis inhibitors has been attributed to enhanced direct killing of cancer cells, principally by macrophage-mediated ADCP." (PMID 35538512, 2022). "Up to now, there are still challenges in activating macrophage effectively, as a result of binding signal regulatory protein alpha (SIRPα) to CD47 on cancer cells." (PMID 35958612, 2022). "The signal regulatory protein α (SIRPα)/CD47 axis has emerged as an important innate immune checkpoint that allows cancer cells to escape phagocytosis by macrophages." (PMID 36325334, 2022). "Phagocytosis checkpoints, including PDCD1, LILRB1, SIGLEC10, and SIRPα are significantly for the function of TAMs in many cancers." (PMID 35317832, 2022). "Human SIRPα-humanized immunodeficient mice were used in cancer models for evaluating the in vivo antitumor efficacy of BR105." (PMID 35256517, 2022). "CD47 is commonly overexpressed on the cell surface of many cancers, providing a “Don't eat me” signal that engages SIRPα on macrophages and prevents phagocytosis." (PMID 36369063, 2022). "Overexpressed CD47 interacts with SIRPα on myeloid cells to help multiple malignant tumors escape immunosurveillance." (PMID 35860564, 2022). "Myeloid checkpoint inhibition by blockade of CD47/SIRPα interactions is a clinically advanced approach to improve antibody-based cancer immunotherapy." (PMID 36052078, 2022). "Elevated CD47 expression in some cancers is associated with decreased survival and limited clearance by phagocytes expressing the CD47 counterreceptor SIRPα." (PMID 33925464, 2021). "Especially, combined CD47/SIRPα with PD-1/PD-L1 checkpoints blockade will be preferred to inhibit cancer cell immune evasion." (PMID 34512146, 2021). "CD47, a cell surface molecule overexpressed by several cancer types that facilitates immune escape from macrophages, dendritic cells and natural killer cells, and its ligand SIRPα, have emerged as potential therapeutic targets." (PMID 34944850, 2021). "Several humanized CD47 antibodies and SIRPα decoys have entered clinical trials as cancer therapeutics." (PMID 33925464, 2021). "Targeting CD47 respectively SIRPα and therefore targeting the innate immune system provides a novel approach in cancer therapy." (PMID 34276685, 2021). "Blocking the interaction between CD47 and SIRPα has proven to be effective in removing cancer cells." (PMID 33629544, 2021). "Such high CD47 expression was proposed to protect cancer stem cells from SIRPα-dependent macrophage clearance, but a cell-autonomous signaling function of CD47 in cancer stem cells was not considered." (PMID 33925464, 2021). "Its extracellular domain (ECD) is a cell surface marker of self that binds SIRPα and inhibits macrophage phagocytosis, and cancer immuno-therapy approaches in clinical trials are focused on blocking CD47/SIRPα interaction." (PMID 34471125, 2021).